G6PC3 (glucose-6-phosphatase catalytic subunit 3)
Description:
Hydrolyzes glucose-6-phosphate to glucose in the endoplasmic reticulum. May form with the glucose-6-phosphate transporter (SLC37A4/G6PT) a ubiquitously expressed complex responsible for glucose production through glycogenolysis and gluconeogenesis. Probably required for normal neutrophil function.
Synonyms: UGRP; SCN4
Tractability: Antibody: UniProt predicts a signal peptide or a membrane-spanning region.
Gene: Protein-coding gene on chromosome 17 (44,070,620 to 44,082,151, forward strand). Ensembl gene ENSG00000141349.
Subcellular location: Endoplasmic reticulum membrane
Subcellular location (Human Protein Atlas): Endoplasmic reticulum
Pathways (Reactome):
Disease: Severe congenital neutropenia type 4 (G6PC3)
Metabolism: Gluconeogenesis
Gene Ontology:
Molecular function: glucose-6-phosphatase activity
Biological process: gluconeogenesis; glucose 6-phosphate metabolic process
Cellular component: endoplasmic reticulum; membrane; endoplasmic reticulum membrane
Genetic constraint (gnomAD): Loss-of-function variants: 29 observed, 39.24 expected, observed/expected ratio (o/e) 0.74, 90% interval 0.55 to 1.01. The upper end of that interval is the gene's LOEUF score, 1.01, which puts it in group 4 of 6, group 1 being the genes least tolerant of losing a copy. Missense variants: 374 observed, 449.29 expected, observed/expected ratio (o/e) 0.83, 90% interval 0.76 to 0.91. Synonymous variants: 192 observed, 181.34 expected, observed/expected ratio (o/e) 1.06, 90% interval 0.94 to 1.19.
Gene-disease validity (ClinGen):
ClinGen rates the evidence that G6PC3 causes each of these diseases.
autosomal recessive severe congenital neutropenia due to G6PC3 deficiency (autosomal recessive): Definitive.
Homologues: Orthologues: chimpanzee G6PC3 (99% identical), macaque G6PC3 (99% identical), pig G6PC3 (92% identical), dog G6PC3 (91% identical), guinea pig G6PC3 (86% identical), mouse G6pc3 (84% identical), rabbit G6PC3 (81% identical), rat G6pc3 (76% identical), zebrafish g6pc3 (44% identical), tropical clawed frog g6pc3.1 (43% identical), Drosophila melanogaster G6P (21% identical). Paralogues in human: G6PC1 (34% identical), G6PC2 (34% identical).
Diseases named in the same sentence as G6PC3 in open-access papers:
G6PC3 is named in the same sentence as 60 diseases in open-access papers, as found by Europe PMC text mining. Sharing a sentence is not in itself a finding about the gene and the disease. The quoted sentences say what the papers report.
neutropenia (27 papers, 2011 to 2025). A decrease in the number of neutrophils found in the blood. "Another remarkable example of a metabolite repair defect, at the center of this review article, is the genetically inherited neutropenia found in glycogen storage disease type Ib (GSDIb) and G6PC3 deficiency." (PMID 40958355, 2025). "Neutropenia in Glycogen Storage Disease Type Ib (GSDIb) and G6PC3 deficiency results from defects in metabolite repair, leading to the accumulation of 1,5‐anhydroglucitol‐6‐phosphate (1,5‐AG6P)." (PMID 40958355, 2025). "As previous reports suggest that G6PC3 deficiency can lead to death from severe infections when neutropenia is left untreated, prompt diagnosis and provision of treatments are critical." (PMID 39041036, 2024). "As previous reports suggested that G6PC3 deficiency can lead to death from severe infections when neutropenia is left untreated, prompt diagnosis and provision of treatments are critical." (PMID 39630167, 2024). "The neutropenia observed in G6PC3-deficient patients is driven by the intracellular accumulation of the metabolite 1,5-anhydroglucitol-6-phosphate (1,5-AG6P) that inhibits glycolysis." (PMID 39630167, 2024). "Inspired by this observation, we have recently repurposed empagliflozin, one of the available SGLT2-inhibitors, to treat neutropenia and neutrophil dysfunction in GSD1b and G6PC3-deficient patients." (PMID 37594549, 2023). "We next focused on the investigation of the kinetic characteristics of the human active isoforms of SGLT4 and SGLT5, because of their possible association with the neutropenias in GSD1b and G6PC3-deficiency." (PMID 37594549, 2023). "In this context, the treatment of the neutropenia associated with GSD1b and G6PC3 deficiency with SGLT2 inhibitors offers a clear improvement compared to previous therapeutic approaches." (PMID 37238286, 2023). "This aspect of the direct inhibition of SGLT5 by gliflozins can be relevant when one considers the repurposing of gliflozins to treat the neutropenia caused by deficiencies in G6PC3 and G6PT." (PMID 37594549, 2023). "In 2019 Veiga-Da-Cunha and colleagues discovered the essential role of G6PT in neutrophils, which explains neutropenia in GSD1b and Glucose-6-Phosphatase Catalytic Subunit 3 (G6PC3)-deficient patients." (PMID 36507137, 2022). "The major phenotype of SCN4 patients with G6PC3 deficiency is severe peripheral blood neutropenia, and almost two thirds of SCN4 patients demonstrate intermittent thrombocytopenia." (PMID 34305938, 2021). "Its deficiency results in Glycogen Storage Disease type Ib,21, 22 which combines the same metabolic symptoms as G6PC1 deficiency with a severe neutropenia similar to that observed in G6PC3 deficiency." (PMID 31691304, 2020). "In myeloid phenotype, SLC37A4 and G6PC3 together are required to maintain neutrophil homeostasis and their deficiency leads to immune deficiency, characterized by neutropenia and neutrophil dysfunction." (PMID 32005221, 2020). "G6PC3 deficiency should be considered as part of the differential diagnoses in any patient with unexplained congenital neutropenia." (PMID 23758768, 2013). "The haematological phenotype of G6PC3 deficiency is variable but severe neutropenia in peripheral blood (neutrophils count below 0.5×109/L) is present in all reported patients." (PMID 23758768, 2013). "If 1,5-AG levels were to be lower, this suggest that indeed remogliflozin could be a better gliflozin to prescribe for the SGLT2-therapy that is now used to treat neutropenia in GSD1b and G6PC3-deficient patients." (PMID 37594549, 2023). "Next, a deficiency in G6PC3 was shown to lead to neutropenia in mice, and mutations in G6PC3 explained a still unknown form of severe congenital neutropenia." (PMID 37238286, 2023).
neutropenia (continued). "The deficiency of G6PC3 is known to cause neutropenia; however, its role in lymphocytes is unclear." (PMID 35886000, 2022). "G6PC3 deficiency can also result in isolated non-syndromic severe neutropenia." (PMID 23758768, 2013). "Finally, myelokathexis is not pathognomomic of WS, as it is observed in other situations such as in neutropenia linked to the glucose 6 phosphatase, catalytic subunit 3 (G6PC3), CXCR2 loss-of-function mutations or in gastric cancer." (PMID 23009155, 2012). "Furthermore, our results also hint that the less specific SGLT2-inhibitor remogliflozin, versus the commonly used empagliflozin, could be a better gliflozin to be repurposed to treat neutropenia in G6PC3-deficient and GSD1b patients." (PMID 37594549, 2023). "Importantly, G6PC3 deficiency results in Severe Congenital Neutropenia type 4 (SNC4), a type of neutropenia similar to that present in GSDIb." (PMID 40958355, 2025). "In addition, rare causes of neonatal neutropenia include severe congenital neutropenia due to gene mutations, such as ELANE, HAX1, and G6PC3, as well as neonatal alloimmune neutropenia caused primarily by maternally derived anti-neutrophil antibodies." (PMID 40722810, 2025). "Neutropenia is one of the symptoms of Wolcott-Rallison syndrome caused by mutations in PERK, encoded by the EIF2AK3 gene, and heightened ER stress was reported in neutropenias caused by mutations in ELANE and glucose-6-phosphate subunit α gene (G6PC3)." (PMID 39962231, 2025). "The lack of G6PT activity is the underlying cause of neutropenia in glycogen storage disease type 1b (GSD1b), whereas the missing G6PC3 activity is responsible for severe congenital neutropenia type 4 (SCN4)." (PMID 39548727, 2025). "Interestingly, failure to eliminate a phosphorylated glucose analog led to neutropenia in patients with SLC37A4 and G6PC3 deficiency." (PMID 38034009, 2023). "As SCN4 patients could be easily missed, it is recommended to consider G6PC3 mutation for any case of congenital, unexplained neutropenia." (PMID 37296469, 2023). "IBD as a complication of neutrophil-centered PID is not unique to G6PC3 deficiency, as it is also seen in other primary neutropenias and in chronic granulomatous disease (CGD)." (PMID 29163546, 2017). "The majority of patients described with G6PC3 deficiency have additional non-haematological features that, in a clinical setting, help to distinguish G6PC3 deficiency from other causes of neutropenia." (PMID 23758768, 2013). "The reason for this variability in the phenotype of G6PC3 deficiency is not clear but it emphasises the importance of considering G6PC3 deficiency as a possible cause of neutropenia even if the bone marrow does not show the maturation arrest of the myeloid cell line." (PMID 23758768, 2013). "A transmembrane protein of the Golgi apparatus is also involved in other disorders comprising neutropenia, such as glycogen storage disease Ib (SLC37A4), G6PC3 and Cohen's disease, but whose phenotypic expression also involves other systems." (PMID 21595885, 2011). "Morphologic abnormalities due to abnormal differentiation in myeloid cells are also encountered in congenital, cyclic, dysgranulopoietic neutropenia cases with or without the WAS, GFI-1, and G6PC3 mutations, in myelodysplastic syndrome, and in a number of non-malignant disorders." (PMID 30040071, 2018). "Therefore, G6PC3 defects should be considered in any case of congenital, unexplained neutropenia regardless of the clinical phenotype." (PMID 25391451, 2014).
congenital neutropenia (17 papers, 2011 to 2025). "G6PC3 deficiency is a monogenic immunometabolic disorder that causes syndromic congenital neutropenia." (PMID 39041036, 2024). "An adult patient with congenital neutropenia and inflammatory bowel disease, a condition which can lead to fatal infections, showed clinical remission of his G6PC3 deficiency further to haematopoietic stem cell transplantation (HSCT)." (PMID 37946251, 2023). "For instance, G6PC3 deficiency is the most common cause of severe congenital neutropenia in Israel; 25% of diagnosed SCN patients." (PMID 37296469, 2023). "Using whole genome sequencing we identified a homozygous variant in the glucose-6-phosphatase G6PC3 gene [c.911dupC; p.Q305fs*82] in an adult patient with congenital neutropenia, lymphopenia and childhood-onset, therapy-refractory Crohn’s disease." (PMID 31157858, 2020). "We present a patient with congenital neutropenia resulting from bi-allelic variants in the catalytic subunit-3 of glucose-6-phosphatase [G6PC3] whose markers of systemic inflammation and symptoms of therapy-resistant Crohn’s disease resolved with HSCT." (PMID 31157858, 2020). "G6PC3 deficiency typically causes severe congenital neutropenia, associated with susceptibility to infections, cardiac and urogenital abnormalities." (PMID 29163546, 2017). "G6PC3 deficiency should be part of the diagnostic screen of any patient with severe congenital neutropenia." (PMID 23758768, 2013). "Recently, a novel syndrome associating various organ abnormalities, including cardiac defects, urogenital abnormalities, inner ear hearing loss, and congenital neutropenia, has been described, caused by mutations in the glucose-6-phosphatase catalytic subunit 3 (G6PC3) gene." (PMID 37521840, 2022). "G6PC3 deficiency is characterized by severe congenital neutropenia, recurrent bacterial infections, intermittent thrombocytopenia in many patients, a prominent superficial venous pattern and a high incidence of congenital cardiac defects and uro-genital anomalies." (PMID 23758768, 2013). "Genetic variants in G6PC3, JAGN1, and VPS13B affect the number and function of neutrophils (rather than their migration) which consequently cause different forms of severe congenital neutropenia (SCN)." (PMID 38550576, 2024). "In addition to G6PC3 deficiency, mutations in ELANE, GFI1, HAX1, CSF3R and WAS are known to cause congenital neutropenia." (PMID 23758768, 2013). "Antenatal diagnosis has already been performed for the following disorders: severe congenital neutropenia with pathogenic ELANE mutations, Shwachman-Diamond syndrome, WHIM syndrome and glycogen storage disease type Ib and may be offered for many other entities, such as HAX1 and G6PC3." (PMID 21595885, 2011). "Two of these three proteins are involved in congenital neutropenia: the translocase (SLC37A4), previously named G6PT1, transports glucose 6 phosphate between the cytoplasm and the lumen of the endoplasmic reticulum, while G6PC3 is a catalytic protein." (PMID 21595885, 2011).
inflammatory bowel disease (3 papers, 2013 to 2023). A spectrum of small and large bowel inflammatory diseases of unknown etiology. "At least five patients, including two sibling pairs, with G6PC3 deficiency have been described with inflammatory bowel disease (IBD)." (PMID 23758768, 2013).
glioblastoma (2 papers, 2023 to 2024). The most malignant astrocytic tumor (WHO grade IV). "Moreover, high mRNA expression of G6PC3 was associated with poor overall survival in glioblastoma, as validated by TCGA database." (PMID 38449509, 2024). "Since G6PC3 might be a key molecule of glioblastoma under hypoxic condition thorough previous evaluation, prognostic analysis in glioblastoma was performed whether G6PC3 expression is associated with the survival." (PMID 38449509, 2024). "G6PC3 was affluently expressed in glioblastoma tissues with coincidentally high 18F-FDG and 18F-FMISO accumulation." (PMID 38449509, 2024). "Among the glioblastoma patients who received gross total resection, mRNA expressions of G6PC3 in the patients with poor prognosis (less than 1-year survival) were significantly higher than that in the patients who survive more than 3 years." (PMID 38449509, 2024). "In our study, G6PC3 protein synthesis was found to be consistent with mRNA expression in glioblastoma." (PMID 38449509, 2024). "Recently, G6PC3 has been focused on as a candidate prognostic predictor of glioblastoma through big data gene expression analysis." (PMID 38449509, 2024). "First, using different cohorts in our archive, the G6PC3 mRNA expression of glioblastoma tissues was investigated in two groups of patients according to their prognosis (Table." (PMID 38449509, 2024). "U87 glioblastoma monolayer cells were transiently transfected with a scrambled sequence (siScrambled, white bars) or siRNA directed against G6PC3 (siG6PC3, black bars), or SLC37A4 (siSLC37A4, black bars)." (PMID 38034009, 2023). "In addition, G6PC3 mRNA expression in 18F-FMISO high-accumulated glioblastomas was significantly higher than that in 18F-FMISO low-accumulated glioblastomas (P < 0.01)." (PMID 38449509, 2024). "Therefore, G6PC3 is a potential key molecule of glucose metabolism under hypoxia in glioblastoma." (PMID 38449509, 2024). "G6PC3 expression was elevated in tissues of glioblastoma with higher 18F-FDG and 18F-FMISO accumulation, and also, G6PC3 elevation was related to the poor prognosis in another independent cohort as well as TCGA database, indicating that it could become a prognostic marker in glioblastomas." (PMID 38449509, 2024).
glioma (2 papers, 2023 to 2024). A benign or malignant brain and spinal cord tumor that arises from glial cells (astrocytes, oligodendrocytes, ependymal cells). "The knockdown of G6PC3 and SLC37A4 in neurospheres resulted in a significant reduction in the expression levels of CSC markers, including EMT biomarkers, all collectively associated with stemness, self-renewal capacity, and invasive properties of glioma stem cells." (PMID 38034009, 2023). "Although G6PC3 has been less likely known to correlate with 18F-FDG uptake in glioma, a study reported that the maximum SUV of 18F-FDG uptake correlated with G6PC3 mRNA expression in intrahepatic cholangiocarcinoma." (PMID 38449509, 2024). "Higher expression in G6PC3, SLC37A2, and SLC37A4 was found in GBM tumor tissues in comparison to low-grade glioma and healthy tissue." (PMID 38034009, 2023). "Next, qPCR analysis revealed that the expression of G6PC3, SLC37A2, and SLC37A4 was considerably higher in all four glioma cell lines tested when compared to HepG2 cells." (PMID 38034009, 2023). "No study has reported the effects of hypoxia on G6PC3 mRNA expression in glioma." (PMID 38449509, 2024).
hepatocellular carcinoma (2 papers, 2020 to 2023). A malignant tumor that arises from hepatocytes. "High expressed Coronin 3 was reported to promote the progression of hepatocellular carcinoma cells by inhibiting the expression of G6PC3." (PMID 32953881, 2020). "Consistent with our in silico data analysis, functional experiments were performed using several established GBM-derived cell lines in which high expression of G6PC3, SLC37A2, and SLC37A4 in comparison to HepG2 hepatoma cells was observed." (PMID 38034009, 2023).
myelodysplastic syndrome (2 papers, 2018 to 2025). A clonal hematopoietic disorder characterized by dysplasia and ineffective hematopoiesis in one or more of the hematopoietic cell lines. "Overall, 16 patients (17.2%) had pathogenic variants, including FANCA, BRCA2, PMS2, ELANE, G6PC3 and VPS13B in patients with idiopathic neutropenia, and GATA2 in patients with suspected myelodysplastic syndrome." (PMID 40358701, 2025).
3MC syndrome (1 paper, 2023). "Vesico‐renal‐genital anomaly is manifested in CHARGE syndrome, G6PC3 deficiency, and Malpuech, Michels, Mingarelli, and Carnevale (3MC) syndrome." (PMID 37102642, 2023).
Autoimmunity (1 paper, 2020). The occurrence of an immune reaction against the organism's own cells or tissues. "Nevertheless, the generally low prevalence of autoimmune diagnoses could also result from the CDG represented in our group which lacks (e.g., G6PC3-, SLC37A4- and GALNT3-CDG) more extensive autoimmunity reports." (PMID 32635232, 2020).
Azoospermia (1 paper, 2024). Absence of any measurable level of sperm,whereby spermatozoa cannot be observed even after centrifugation of the semen pellet. "This study reveals a new aspect of G6PC3 function in male meiosis, offering insights into whether mutations inG6pc3 may contribute to nonobstructive azoospermia or related disorders." (PMID 39420835, 2024).
brain cancer (1 paper, 2023). A primary or metastatic malignant neoplasm affecting the brain. "In conclusion, our study highlights an original and underestimated potential of G6PC3 and SLC37A4 as prognostic markers and therapeutic targets in brain cancer." (PMID 38034009, 2023).